RACGAP1 (Rac GTPase activating protein 1)
Diseases named in the same sentence as RACGAP1 in open-access papers (continued):
Sharing a sentence is not in itself a finding about the gene and the disease.
tumor (continued). "In terms of clinicopathological correlation, CETN2, MPZL1, RACGAP1, and SNRPB were upregulated in patients with microvascular invasion, and the expression of MPZL1 and SNRPB was increased in proportion to the Edmonson tumor differentiation grade." (PMID 35205612, 2022). "Next, we systematically explored the relationship between the expression of 37 common DEGs in tumor tissues and overall survival (OS) rate of HCC patients in TCGA and constructed a novel prognostic model composed of five genes (AURKA, PZP, RACGAP1, ACOT12 and LCAT)." (PMID 34336648, 2021). "Based on the findings from TIMER, we proposed that LMNB1, TK1, ZWINT, and RACGAP1 are mainly expressed in PCa cells rather than immune cells, and their functions do not relate to immunological regulation of the tumor microenvironment." (PMID 31306099, 2019). "Finally, immunoblotting showed that expression of RACGAP1 and phosphorylated ERK was higher in RACGAP1P 3’UTR-expressing tumours than control tumours." (PMID 31160556, 2019). "In several types of cancer, recent studies have identified upregulated expression of RacGAP1 (also known as MgcRacGAP or hCYK-4), a member of the guanine triphosphatase (GTPase) activation protein (GAP) family and suggested its potential role in promoting tumor progression." (PMID 31426369, 2019). "Furthermore, the expression of RACGAP1 correlated significantly with the tumor stage in BLCA after RC, and RACGAP1 was strongly expressed in the early stages of NMIBC patient samples." (PMID 31766561, 2019). "Nevertheless, studies increasingly reveal that RACGAP1 activates Rho-GTPases rather than inactivates them, which makes it a cancer-promoting protein that is different from other GAPs, which are usually known to be tumor suppressors." (PMID 39858398, 2024). "Furthermore, only one tumor, DLBC, revealed a significant negative association between RACGAP1 expression and MSI." (PMID 36430577, 2022). "Putting the results of RACGAP1 expression and MDSC and NKT infiltration together, we can conclude that the upregulation of RACGAP1 expression could be used as a marker for a poor immune response against a growing tumor." (PMID 36430577, 2022). "Rac GTPase-activating protein 1 (RacGAP1), one of the specific GTPase-activating proteins (RhoGAP), which stimulate the intrinsic GTPase activity of Rho proteins and restore them to the inactive state of binding to GDP, can regulate Rac1 and CDC42 proteins to drive tumor growth." (PMID 35831303, 2022). "Our data suggest that RACGAP1 acts as an oncoprotein rather than a tumor suppressor in PDAC cells." (PMID 30866526, 2019). "In addition, RACGAP1 expression levels were increased across different stages of LUAD (compared to normal lung tissues, all P < 0.05), with late-stage tumor tissues exhibiting higher expression levels than did early-stage tumor tissues (stage 4 vs. stage 1; P < 0.05)." (PMID 38622149, 2024). "The tumor samples of these patients were compared with the samples from non-treated patients for their respective Ki-67, TOP2A and RacGAP1 mRNA and protein levels as determined by means of the different evaluation methods." (PMID 27259241, 2016). "However, we only observed the physical interaction of SHCBP1 with RACGAP1 and MKLP1, but not with PLK1 in asynchronous tumour cells, suggesting that SHCBP1 may only interact with PLK1 in the mitotic phase." (PMID 38365687, 2024).
cancer (52 papers, 2011 to 2025). A tumor composed of atypical neoplastic, often pleomorphic cells that invade other tissues. "Studies have shown that RacGAP1 promotes cell proliferation, migration and invasion as well as its overexpression is associated with various cancers." (PMID 40497948, 2025). "Following examining the differential expression of RACGAP1 in normal and malignant tissues, we intended to investigate the association between RACGAP1 expression and cancer staging." (PMID 36430577, 2022). "In this study, we found that RacGAP1 expression is increased after irradiation and associated with cancer cell invasion." (PMID 31426369, 2019). "Cancers in other segments of the digestive tract are also associated with RACGAP1." (PMID 39858398, 2024). "The Rac GTPase activating protein 1 (RacGAP1) is a previously unknown but very interesting proliferation marker; it is upregulated in many malignant tumors and is associated with a poor patient outcome." (PMID 27259241, 2016). "In particular, we obtained an effective silencing of RacGAP1 by siRNA transfection with the aim to observe the effect of its absence on cancer hallmarks." (PMID 40497948, 2025). "RACGAP1 regulates Rho GTPases, which modulate cytoskeleton dynamics, cell migration, and invasion in cancer." (PMID 41009526, 2025). "The effects of RacGAP1 silencing on cancer hallmarks were then evaluated using cell-based assays, i.e., cell proliferation, migration and invasion." (PMID 40497948, 2025). "Overall, the results of the described analyses of patient cohorts strongly suggest an oncogenic role of RacGAP1, thus prompting us to experimentally validate its involvement in cancer." (PMID 40497948, 2025). "Recent studies have demonstrated that RACGAP1 is a valuable marker for predicting outcomes and understanding the immune response in various cancers, including liver cancer." (PMID 40421085, 2025). "This article mainly reviews the expression regulation of RACGAP1 and its cancer-promoting functions through oncogene expression mediation and Rho-GTPase activation." (PMID 39858398, 2024). "RACGAP1 has been reported to overexpress in multiple cancers, participate in the development of cancers and induce drug resistance." (PMID 39858398, 2024). "Although RACGAP1 is found to be correlated with various molecules in cancers, these studies rely on bioinformatics, and more experiments are needed to elucidate how RACGAP1 promotes cancer development." (PMID 39858398, 2024). "Current studies indicate that RACGAP1 is generally upregulated by the aberrant expression of non-coding RNAs and transcriptional factors in various cancers." (PMID 39858398, 2024). "Current studies support that RACGAP1 promotes cancers by mediating its downstream oncogenic gene expression in signal pathways, and activating Rho-GTPases instead of inactivating Rho-GTPases, despite being named a Rho-GTPase-activating protein." (PMID 39858398, 2024). "This gene has been extensively studied in different cancers, but in vivo and in vitro studies have only recently shown that RACGAP1 is over-expressed in HCC." (PMID 39272711, 2024). "It appears that RACGAP1 contributes to the cancer progression through both GTPase activity-dependent and independent mechanisms." (PMID 38898473, 2024). "As a supplement to these results, it was discovered that STAT3 can bind the RACGAP1 promoter to upregulate its transcription in multiple cancers." (PMID 39858398, 2024). "As a cancer-promoting protein, RACGAP1 is upregulated in most cancers, and the abnormal expression can result from non-coding RNAs or transcriptional factors." (PMID 39858398, 2024). "In ESC, E2F3 overexpression induces RACGAP1 expression, thereby enhancing the cancer-promoting effect of RACGAP1." (PMID 37504265, 2023). "To explore the expression of RacGAP1 in CC, we analyzed a profile from the Oncomine database named Pyeon Multi-cancer." (PMID 35831303, 2022).
cancer (continued). "For this purpose, the current study applied a pan-cancer analysis for the oncogenic behavior of RACGAP1." (PMID 36430577, 2022). "AURKB promotes survival of cancer cells by cell cycle progression with phosphorylating a series of downstream substrates, including RacGAP1." (PMID 35222021, 2022). "This comprehensive study demonstrates the predicted molecular roles of RACGAP1 in several cancer types in addition to its influence on clinical prognosis." (PMID 36430577, 2022). "In our study, we found that RacGAP1 was upregulated in cancer tissues and correlated with histological grade." (PMID 35831303, 2022). "The results demonstrated that RACGAP1, a highly expressed gene across several types of tumors, correlated with a poor prognosis in several types of human cancers." (PMID 36430577, 2022). "The results of both databases indicate that an overall poor clinical outcome is expected with RACGAP1 expression in cancer patients." (PMID 36430577, 2022). "Previous studies demonstrated that RACGAP1 was a cancer‐promoting gene overexpressed in various cancers." (PMID 33252198, 2021). "The activity of RACGAP1 characterized with Rho GTPases is involved in exerting effects in these malignant tumors, however, its functional analyses indicated that its activity is not limited to Rho GTPases." (PMID 34239347, 2021). "Previous studies have uncovered the oncogenic potential of elevated RACGAP1 in a number of malignant tumors." (PMID 34239347, 2021). "RACGAP1 (also referred to as Rac GTPase activating protein 1) is a cytokinesis-regulatory protein which is often overexpressed in multiple cancers." (PMID 32149105, 2020). "Expression of RACGAP1 also impacts invasiveness of cancer cells resulting in significantly poorer prognosis and lymph node and distant metastasis." (PMID 33033514, 2020). "ALDOA and RACGAP1 are tubulin binding proteins important for the microtubule filaments system, and are mainly responsible for metastasis and invasiveness in various carcinomas." (PMID 33379356, 2020). "From our network, we observed that E2F1 regulates POLD1, ASF1B, FOXM1 and RACGAP1 which are up-regulated in all 15 cancer types (Subnetwork)." (PMID 30809433, 2019). "Here, we show that upregulation of RacGAP1 after IR is accompanied by increased invasion activity, and depletion of RacGAP1 significantly suppressed IR-induced cancer cell invasion." (PMID 31426369, 2019). "Given the significant effects of RACGAP1 on cancer recurrence, the regulatory network related to RACGAP1 urgently needed to be explored." (PMID 31160556, 2019). "Cancer cell migration and invasion were significantly inhibited in si-RACGAP1-transfected cells compared with mock- or siRNA-control-transfected PDAC cells." (PMID 30866526, 2019). "Previous studies suggest that RacGAP1 is a potential therapeutic target for the treatment of highly aggressive cancers." (PMID 31426369, 2019). "RacGAP1 signaling is a possible molecular mechanism of CGN effect after IR treatment on cancer cells." (PMID 31426369, 2019). "Based on these data, we conclude that CGN enhances the effect of radiotherapy by suppressing cancer cell survival and invasiveness through the RacGAP1 pathway." (PMID 31426369, 2019). "In clinical studies, RacGAP1 has attracted increasing attention as a predictive biomarker for metastasis and prognosis in several types of cancer." (PMID 31426369, 2019). "Several studies have reported that α5β1-integrin trafficking regulates RacGAP1 activation, which is essential to promote pseudopod extension and cancer cell invasion." (PMID 31426369, 2019). "Protein expression of RacGAP1 was upregulated in several cancer cell lines after radiation, which was significantly suppressed by CGN treatment." (PMID 31426369, 2019).
cancer (continued). "Given that the stability and nuclear translocation of the intracellular β-catenin are known to impact the Wnt signaling pathway, thereby regulating the expression of different genes involved in cancer onset and progression, the level of β-catenin was also evaluated after RacGAP1 silencing." (PMID 40497948, 2025). "Several positive feedback loops of RACGAP1 expression have been proven, while, to our knowledge, negative feedbacks have not been discovered, which may account for its overexpression in cancers." (PMID 39858398, 2024). "Meanwhile, a positive feedback loop is formed in some cancers to promote RACGAP1 expression." (PMID 39858398, 2024). "RACGAP1 has been shown to play essential roles in multiple cancers through its high expression." (PMID 38468345, 2024). "Therefore, in this review, we manage to elucidate the expression regulation of RACGAP1 in cancers, including its upstream regulation and feedback regulation." (PMID 39858398, 2024). "In addition, RACGAP1 plays a role in regulating the cell cycle and is involved in the progression of other types of cancer." (PMID 38167018, 2024). "This may suggest that the lack of negative feedback regulation is one of the reasons for the overexpression of RACGAP1 in many cancers." (PMID 39858398, 2024). "RACGAP1 usually promotes the development of cancers in signal pathways." (PMID 39858398, 2024). "Several studies have analyzed the role of RACGAP1 in different types of human cancers." (PMID 36430577, 2022). "In addition, RACGAP1 plays a critical role in mitochondrial fission and speeds up mitochondrial renewal and mitochondrial respiration, which leads to cancer cell metastasis." (PMID 35445033, 2022). "What's more, the expression of RacGAP1 in endothelial cells may play a key role in the pathogenesis of cancer by regulating endothelial permeability." (PMID 35831303, 2022). "In addition, ANLN expression was strongly associated with that of DEPDC, KIF14, KIF23, RACGAP1, and CKAP2L genes across cancers." (PMID 35340220, 2022). "Moreover, TRPV1 expression correlated negatively with the expression of RACGAP1, another marker for cell proliferation, in pan-cancer (p = 5.80 × 10−98; r = −0.29) as well as in five cancer types (p < 0.001)." (PMID 36304985, 2022). "Previous study emphasized that RACGAP1 could enhance proliferation of cancer cells through Hippo signaling pathway." (PMID 35958019, 2022). "Therefore, cancer cell cycle arrest and apoptosis that occur in the presence of RACGAP1 knockdown is partly due to failure of DNA damage repair induced by LIG3 suppression." (PMID 34239347, 2021). "Furthermore, knockdown of RacGAP1 effectively suppressed the IR-induced invasion activity of cancer cells." (PMID 31426369, 2019). "Again, this might be related to the high proportion of advanced stage cancers in our cohort, and a main effect of RACGAP1 at early stages of gastric carcinogenesis cannot be ruled out." (PMID 26778597, 2016). "However, recent studies support that RACGAP1 can activate Rho-GTPases in cancers." (PMID 39858398, 2024). "Therefore, the expression of RACGAP1 in cancers, as well as the regulatory mechanisms, may remain to be further studied." (PMID 39858398, 2024). "Besides the predictive role of RacGAP1 in cancers, it may also be a new target in developing novel chemotherapy drugs." (PMID 35831303, 2022). "In addition, exogenous overexpression of RACGAP1P 3’UTR in different human cancer cell lines could induce RACGAP1 expression showed by QPCR results." (PMID 31160556, 2019). "Taken together, these results suggest that CGN may enhance the effectiveness of radiation in cancer therapy by decreasing cancer cell viability and suppressing both radiation-induced invasive activity and distal metastasis through downregulating RacGAP1 expression." (PMID 31426369, 2019).
cancer (continued). "In all, although it seems that GEF antagonizes the effect of GAP, recent studies suggest that RACGAP1 can coordinate with ECT2 to promote the proliferation and migration of cancer cells." (PMID 39858398, 2024). "Among the five genes, the mechanism of HMGA1, MPZL1, RACGAP1, and SNRPB in cancer progression were reported in several prior studies." (PMID 35205612, 2022). "Abnormal expression of Rac GTPase activating protein 1 (RACGAP1) was involved in the pathogenesis and progression of plenty malignant tumors." (PMID 35958019, 2022). "Furthermore, TMB and MSI were connected with RACGAP1 expression in various human malignancies; hence, these results could designate RACGAP1 as a reliable prognostic biomarker, a marker for patients’ responsiveness to immunotherapy, and a promising target for cancer therapeutics." (PMID 36430577, 2022). "Our present data showed that RACGAP1 was overexpressed in PDAC clinical specimens, and silencing of RACGAP1 inhibited cancer cell migration and invasion." (PMID 30866526, 2019). "Strikingly, there is evidence thatANLN, ECT2, PRC1,RACGAP1, ASPM, and PLK1 areupregulated in a variety of human cancers and that their overexpression oftencorrelates with poor outcome (see for example and references therein)." (PMID 21386884, 2011). "Since many articles reveal that RACGAP1 functions in a GAP-activity-independent way, it seems that the GAP domain activity of RACGAP1 is not exhibited in the development of cancers." (PMID 39858398, 2024). "Again, no cancers in the panel analyzed witnessed a positive correlation between RACGAP1 expression and NKT infiltration." (PMID 36430577, 2022). "Although several studies have tried to analyze the oncogenic of RACGAP1 in several human cancers, there is a lack of a comprehensive study that can deal with the effect of RACGAP1 from many perspectives in a list of several human tumors." (PMID 36430577, 2022). "Namely, FOXM1 promotes epithelial-mesenchymal transition and metastasis formation for breast and various other cancers, RRM2 contributes to poor survival and tamoxifen resistance development, while expression levels of CDK1, PLK1 and RACGAP1 were shown to be prognostic markers." (PMID 33852600, 2021). "Although Rac is considered to antagonize RhoA, studies suggest that RACGAP1 can keep Rac or RhoA activated in different cancers, and the subsequent events of Rac and RhoA activation are not always irrelevant, implying that RACGAP1 can coordinate Rac and RhoA in some situations." (PMID 39858398, 2024). "Taken together, RACGAP1 may promote STAT3 phosphorylation, nuclear translocation and the expression of STAT3 downstream molecules, such as survivin, to lead to the development of cancers." (PMID 39858398, 2024). "Notably, no cancer from the analyzed panel witnessed a negative correlation between RACGAP1 expression and MDSC infiltration." (PMID 36430577, 2022). "Likewise, we observed significant positive correlations of TOP2A and RACGAP1 expression levels with DEPTH scores in 13 and 15 cancer types, respectively (FDRsp < 0.05), as well as in pan-cancer (TOP2A: p = 6.98 × 10−93, ρ = 0.21; RACGAP1: p = 4.14 × 10−157, ρ = 0.28)." (PMID 32917965, 2020). "We speculate that the dominant uptake may be by non-parenchymal cells like Kupffer cells in the liver and macrophages in the spleen, where the biological function of RacGAP1 might not directly translate to driving proliferation in the same manner as in cancer cells." (PMID 41230850, 2025). "On the contrary, only two cancers, TGCT and LAML, did not exhibit significant differences and upregulation of RACGAP1 in healthy tissues compared to malignant tissue, respectively." (PMID 36430577, 2022). "To date, there is no report linking RACGAP1 to ATC, but its importance in the development of other cancers has been revealed." (PMID 30774662, 2019).
adenocarcinoma (2 papers, 2021 to 2025). A common cancer characterized by the presence of malignant glandular cells. "Overall, our findings indicate that RacGAP1 plays an oncogenic role in adenocarcinoma, contributing to the abnormal activation of the Wnt/β-catenin signaling pathway." (PMID 40497948, 2025).
infection (2 papers, 2019 to 2021). The state of being infected such as from the introduction of a foreign agent such as serum, vaccine, antigenic substance or organism. "In this work, we show that CiaD binds to the host cell protein IQGAP1 to displace RacGAP1 using affinity pull-down experiments coupled with LC–MS/MS and immunoblots, yeast-two hybrid (Y2H), and C. jejuni-host cell infection assays." (PMID 33637714, 2021). "In addition, a number of genes associated with GTPase activities, which included GIMAP2, RACGAP1, AGBL5 and RAP1GDS1, were down-regulated during the early phase of infection." (PMID 30789917, 2019). "However, we found that the association of RacGAP1 with IQGAP1 was reduced approximately 50% upon infection with a C. jejuni wild-type strain but not upon infection with a ∆ciaD mutant (p < 0.05)." (PMID 33637714, 2021).